NPY (neuropeptide Y)
Diseases named in the same sentence as NPY in open-access papers (continued):
Sharing a sentence is not in itself a finding about the gene and the disease.
osteoporosis (20 papers, 2016 to 2025). A condition of reduced bone mass, with decreased cortical thickness and a decrease in the number and size of the trabeculae of cancellous bone (but normal chemical composition), resulting in increased fracture incidence. "In AD, the accumulation of amyloid-β and tau protein, key hallmarks of neurodegeneration, has been implicated in osteoporosis development by modulating neuropeptide Y (NPY) expression, which impacts bone density and the trabecular architecture." (PMID 40564162, 2025). "It was suggested that the expressions of NPY and Y1R in bone tissue were associated with the bone metabolism in osteoporosis." (PMID 32381754, 2020). "These new NPY peptides reduced bone loss in ovariectomized mice more effectively than the full-length NPY, suggesting their potential application in osteoporosis." (PMID 29109742, 2017). "And in a mouse model of ovariectomy-induced osteoporosis, NPY treatment ameliorated bone loss by decreasing the number of osteoclasts via increased HSPC mobilization." (PMID 29109742, 2017). "Finally, we investigated the impact of γ‐Oryzanol on osteocyte NPY production and bone‐fat imbalance during aging and estrogen deficiency‐induced osteoporosis." (PMID 34719888, 2021). "Due to the substantial distribution of Y1R in bone, NPY-Y1R signaling is involved in the pathogenesis of various human musculoskeletal disorders, including osteoporosis, fracture, inflammation, and osteoarthritis." (PMID 36428510, 2022). "In the clinical setting, micro-CT and NPY optical density (MOD) of subchondral cancellous bone were compared between osteoporosis and osteoarthritis patients and showed that the bone volume fraction (BV/TV;%), trabecular thickness (Tb." (PMID 34421823, 2021). "Herein, we report that during aging and osteoporosis, osteocytes secrete excess NPY to promote adipogenic differentiation of BMSCs at the expense of osteogenesis through Y1R." (PMID 34719888, 2021). "N; mm−1) were lower in osteoporosis patients than osteoarthritis patients; however, the NPY MOD value of subchondral cancellous bone was higher in the osteoporosis patients." (PMID 34421823, 2021). "Collectively, these results suggest that SNS promotes whereas PSNS attenuates bone‐fat imbalance during skeletal aging and osteoporosis through their opposite regulation of osteocyte NPY production." (PMID 34719888, 2021). "Here it is found that osteocytes, the most abundant bone cells, promote adipogenesis and inhibit osteogenesis of BMSCs by secreting neuropeptide Y (NPY), whose expression increases with aging and osteoporosis." (PMID 34719888, 2021). "In ovariectomized rat models, a decrease in NPY and Y2R in the brain was observed in addition to development of osteoporosis." (PMID 34421823, 2021). "A recent study has suggested that NPY signaling mediated glucocorticoid-induced osteoporosis in mice." (PMID 28009825, 2016). "The specific mechanism by which NPY affects the behavior of BMSCs during the onset of osteoporosis remains unknown." (PMID 38994021, 2024). "In summary, elevated levels of neuropeptide Y can disrupt normal bone metabolism and osteogenesis by promoting the differentiation of BMSCs into adipocytes, ultimately leading to the development of osteoporosis." (PMID 38994021, 2024). "and the expression of NPY rises with aging and in cases of osteoporosis." (PMID 38979414, 2024). "Above all, it is possible that NPY participates in the pathogenesis of osteoporosis." (PMID 35273572, 2022). "Our study demonstrates an osteocyte NPY‐dependent neuronal control of BMSC fate decision and bone‐fat balance, and suggests that diet‐ or drug‐based therapy that favors ANS balance and reduces osteocyte NPY production is a promising therapeutic option against osteoporosis and skeletal aging." (PMID 34719888, 2021).
osteoporosis (continued). "In recent years, the regulatory effects of NPY on osteogenesis and the involved mechanisms have been revealed, which suggested that NPY could be a novel therapeutic target for osteoporosis." (PMID 29109742, 2017). "A NPY‐mediated brain‐gut‐bone axis has come to light, demonstrating that the overexpression of NPY released by the hypothalamus induces intestinal inflammation and microbiota dysbiosis, where the “leaky gut” releases LPS to induce osteoblast pyroptosis and aggravate osteoporosis in OVX rats." (PMID 37857552, 2023). "In general, NPY system exerts multiple regulatory effects on bone homeostasis at CNS and peripheral levels, suggesting that regulating NPY activity may be a novel strategy for osteoporosis treatment." (PMID 29109742, 2017). "Osteocyte NPY was required for the SNS‐induced promotion and PSNS‐induced inhibition of bone‐fat imbalance and osteoporosis." (PMID 34719888, 2021). "In detail, NPY plays a negative role in the process of osteoporosis." (PMID 35273572, 2022). "Although it has not been reported, we can speculate that the regulation of NPY on the osteogenic differentiation of BMSCs may play a role in the treatment of osteoporosis." (PMID 29109742, 2017). "More importantly, we found that the protein level of NPY in the bone tissue was dramatically increased with aging and with the induction of osteoporosis by OVX surgery in young mice, implying that NPY may be involved in regulating bone homeostasis in skeletal aging and osteoporosis." (PMID 34719888, 2021).
colitis (18 papers, 2008 to 2025). Inflammation of the colon. "Enhanced resistance to DSS-induced colitis has been observed in both NPY-deficient mice and those treated with Y1R antagonists." (PMID 41007974, 2025). "DSS-induced colitis was associated with an increase in circulating neuropeptide Y (NPY), a rise in the hypothalamic expression of cyclooxygenase-2 mRNA and a decrease in the hippocampal expression of NPY mRNA, brain-derived neurotrophic factor mRNA and mineralocorticoid receptor mRNA." (PMID 25414650, 2014). "Although other sources of NPY cannot be excluded, elevated levels of plasma NPY are likely to reflect increased release of the neuropeptide from sympathetic nerve endings, a conclusion that is consistent with other data that colitis is associated with increased sympathetic activity." (PMID 25414650, 2014). "The upregulation of pyyb and y8b observed in infected tilapia resembled findings in rodent colitis models, where NPY expression was induced by pro-inflammatory mediators such as TNF-α and IL-1β." (PMID 41007974, 2025). "Colitis induces a major upregulation of enteric neuronal NPY, which triggers an oxidative and inflammatory response through neuronal nitric oxide synthase activation." (PMID 37014495, 2023). "A model of TNBS-induced colitis in DPP4-/- mice showed higher serum levels of neuropeptide Y (NPY), vasoactive intestinal peptide (VIP) and IL-6, which are all substrates of DPP4, compared to C57BL/6 mice." (PMID 35309368, 2022). "Mice with DSS-induced colitis exhibited more anxiety and less social behaviour than control mice and occurred in parallel with increased circulating IL-6, NPY, and IL-18 levels as well as an increase in hypothalamic Cox-2 mRNA." (PMID 34983592, 2022). "Further evidence for the role of NPY in promoting inflammation in the gut is provided by the fact that NPY knockout (KO) mice are resistant to the induction of DSS colitis." (PMID 26635804, 2015). "In order to validate the observation that NPY mediated increase in nNOS is responsible for increased oxidative stress and subsequent damage in colitis; we induced S.T. colitis in nNOS−/− and NPY−/−/nNOS−/− mice." (PMID 18836554, 2008). "Taken together our data reveal that enteric neurons producing NPY play an important role in modulating inflammation in colitis." (PMID 18836554, 2008). "The NPY−/− mice were resistant to DSS colitis as assessed by histological score, clinical score and blood in stool." (PMID 18836554, 2008). "In summary, our study demonstrates that NPY from enteric neurons is up regulated during colitis and it can regulate the expression of nitric oxide synthase and subsequent nitric oxide production." (PMID 18836554, 2008). "The histological data supported the observations based on clinical analysis and confirmed the protective role of NPY deletion towards the development of colitis." (PMID 18836554, 2008). "Our studies demonstrate a role for the neuronal NOS, along with NPY, in the pathogenesis of colitis." (PMID 18836554, 2008). "In the present study we analyzed the role of NPY in modulating inflammation associated with DSS and Salmonella models of colitis." (PMID 18836554, 2008). "Conversely, suppression of NPY expression through the administration of antisense oligodeoxynucleotides (ODNs) in rats with DSS-induced colitis not only limits leukocyte infiltration but also diminishes TNF-α production, thereby mitigating intestinal inflammation." (PMID 41007974, 2025). "The level of NPY is increased in the hypothalamus and serum of mice suffering from colitis." (PMID 35592257, 2022). "Additionally, NPY also enhances nNOS, which is associated with oxidative stress, in a murine model of DSS colitis." (PMID 26635804, 2015). "(iv) DSS-induced colitis was associated with an increase in circulating IL6, IL18, and NPY, an increased expression of COX-2 mRNA in the hypothalamus, and a decreased expression of BDNF, NPY, and MR mRNA in the hippocampus." (PMID 25414650, 2014).
colitis (continued). "Thus, NPY gene expression is increased in enteric ganglia of DSS-treated mice, and deletion of the NPY gene attenuates the severity of DSS-induced colitis in mice." (PMID 25414650, 2014). "This supports our hypothesis that NPY-nNOS induced nitric oxide is a major determinant of oxidative stress -induced damage in colitis." (PMID 18836554, 2008). "This suggested that NPY-mediated damage in colitis is through nNOS." (PMID 18836554, 2008). "In addition, NPY has a role in the pathogenesis of DSS-induced colitis." (PMID 25414650, 2014). "In vivo, mice with DSS-induced colitis presented with brain region-specific alterations in HPA axis-related peptides, glucocorticoid receptor gene expression, and factors including NPY, NPY receptor Y1, CRF, CRF receptor 1, and BDNF." (PMID 34983592, 2022). "A decrease in TH, NPY and VIP expressing CaMG-neurons was also presented for chemically induced colitis in pigs." (PMID 34246257, 2021). "In particular, NPY levels were shown to be increased in both DSS-induced colitis and TNBS-induced colitis." (PMID 26635804, 2015). "Considering the decreased intestinal NPY and PYY levels in cpe−/− mice, we next analyzed colonic cytokine transcript levels of both genotypes at baseline conditions and after experimental colitis induction via quantitative RT-PCR." (PMID 25051500, 2014). "We examined the role of neuropeptide Y (NPY) and neuronal nitric oxide synthase (nNOS) in modulating colitis." (PMID 18836554, 2008). "Additionally, NPY has been identified as an inducible gene within enteric neurons in both murine IBD and Salmonella typhimurium colitis models." (PMID 41007974, 2025). "Furthermore, the ablation of NPY has been shown to ameliorate tissue injury and barrier disruption, which occurs due to DSS- or S. typhimurium- induced colitis." (PMID 37692784, 2023). "Prior publications have reported that sympathetic responses are altered in IBD, that sympathetic nerves innervate and regulate colon function, and that NPY, a key sympathetic neuroregulator, could play a role in the etiology of DSS-induced colitis." (PMID 31369588, 2019). "It is worth mentioning that the expression of NPY in the hypothalamus tended to increase in mice with DSS-induced colitis, which is similar to the increase in hypothalamic NPY found in mice and rats with TNBS acid-induced colitis." (PMID 25414650, 2014). "Colitis was induced by administration of dextran sodium sulphate (3% DSS) or streptomycin pre-treated Salmonella typhimurium (S.T.) in wild type (WT) and NPY (NPY−/−) knockout mice." (PMID 18836554, 2008). "Our study demonstrates increased colonic expression of NPY in DSS and S.T. colitis." (PMID 18836554, 2008). "Additionally, the other two peptides from same family, neuropeptide Y (NPY) and pancreatic polypeptide, bind to the same receptors as PYY and may also play some unknown functional roles in the experimental colitis mouse model." (PMID 35443853, 2022). "In order to validate the observation that NPY-mediated increase in nNOS is responsible for increased oxidative stress and subsequent damage in colitis, we used S.T. model to study the effect of the absence of nNOS as well as absence of both NPY and NOS in inflammation." (PMID 18836554, 2008).
Ewing sarcoma (18 papers, 2010 to 2026). A small round cell tumor that lacks morphologic, immunohistochemical, and electron microscopic evidence of neuroectodermal differentiation. "Studies on Ewing sarcoma demonstrated the association between high systemic NPY levels and bone metastasis and provided direct evidence for the role of the NPY system in this process." (PMID 36583743, 2023). "Elevated release of NPY by Ewing sarcoma tumours is associated with site-specific metastasis including thoracic extra-osseous, bone and brain." (PMID 29098360, 2018). "A clinical study by the same group recently found that NPY was systemically increased in Ewing sarcoma patients and was associated with metastasis." (PMID 29098360, 2018). "Moreover, hypoxia has been reported to cause aneuploidy in Ewing sarcoma via the HIF-independent DDP4/Neuropeptide Y (NPY)–NPY-Y5 Receptor (Y5R)–Rho A axis." (PMID 38730681, 2024). "Similarly, NPY and its Y5R have been implicated in the motility of Ewing sarcoma, breast, and liver cancer cells." (PMID 33681186, 2020). "In a recent study investigating Ewing sarcoma, it was found that enhanced metastasis to the bone was driven by a hypoxia-induced activation of NPY signaling components." (PMID 40073121, 2025). "Overexpression of NPY in Ewing sarcoma and NB creates auto- and paracrine loops cooperating with endothelial cells, with pro-survival, pro-invasive and angiogenetic activities." (PMID 36583743, 2023). "The EWS-FLI1 fusion protein is an aberrant transcription agent that upregulates genes in Ewing sarcoma (e.g., NPY, Y1R, Y5R) and triggers the malignant transformation in Ewing sarcoma." (PMID 37373115, 2023). "Bone destruction degree in Ewing sarcoma has been positively correlated with the level of NPY release from tumors." (PMID 37373115, 2023). "Circulating NPY level is high in patients with Ewing sarcoma, and a higher level of the peptide was observed in patients with Ewing sarcoma showing tumors with a pelvic/bone origin." (PMID 37373115, 2023). "Tumor hypoxia exacerbates bone metastasis in Ewing sarcoma; this process is mediated by the hypoxia-induced activation of the NPY/Y5R system, leading to RhoA overstimulation, cytokinesis failure and the formation of polyploid Ewing sarcoma cells." (PMID 37373115, 2023). "Studies focusing on Ewing sarcoma revealed that tumour cells with high NPY expression metastasize preferentially to the bone, while the activity of the NPY/Y5R axis induced by hypoxia is crucial for their osseous dissemination." (PMID 36583743, 2023). "It has been suggested that NPY/Y1R/Y5R are involved in maintaining a highly undifferentiated phenotype in Ewing sarcoma because both receptors mediated pluripotency and human embryonic stem cell self-renewal." (PMID 37373115, 2023). "Consistent with this, our previous studies indicated that the NPY-induced migration of hypoxic Ewing sarcoma cells with a cancer stem cell phenotype requires Y2R and Y5R interactions." (PMID 33681186, 2020). "In another NPY-rich tumor, Ewing sarcoma, Y5R was involved in the migration of hypoxic cancer stem cells." (PMID 33681186, 2020). "Under normoxic conditions, NPY acts upon the Y1R and Y5R receptors to stimulate cell death in Ewing sarcoma; however, hypoxia alters the expression of NPY receptors by inducing Y2R expression instead." (PMID 29098360, 2018). "Use of short hairpin RNA (shRNA) to reduce NPY expression in an Ewing sarcoma cell line then injected into mice exhibited, reduced bone destruction as quantified by μCT." (PMID 29098360, 2018). "Our work implicates WT1 as a global regulator of Ewing sarcoma angiogenesis, and future work will clarify how NPY, REST, and WT1 interact." (PMID 24810959, 2014). "DPP9 and DPP8 enzymatic activity can protect Ewing sarcoma cells from neuropeptide Y (NPY)-driven death." (PMID 24223149, 2013).
Ewing sarcoma (continued). "In malignancies originating from neuroendocrine tissues, such as neuroblastoma and Ewing's sarcoma, NPY released from tumor cells seems to be an essential factor involved in their vascularization." (PMID 20508839, 2010). "As a result, exogenous NPY inhibits growth of Ewing's sarcoma xenografts in vivo, despite increase in their vascularization." (PMID 20508839, 2010). "NPY blocked, via Gi-coupled-Y1R, cAMP formation in Ewing sarcoma cells, and the peptide, through the inhibitory guanine nucleotide regulatory protein of adenylate cyclase, also blocked the dopamine-induced cAMP formation in Ewing sarcoma cells (WE-68), but not basal cAMP formation." (PMID 37373115, 2023). "Ewing sarcoma intratumoral blood vessels expressed Y1R; Ewing sarcoma cells express NPY, Y1R, and Y5R, and the peptide via both receptors promoted the death of tumor cells, which was mediated by poly(ADP-ribose polymerase) (PARP-1) and apoptosis-inducing factor (AIF)." (PMID 37373115, 2023). "NPY/Y5R was highly upregulated in distant metastasis in an experimental model of Ewing sarcoma when compared with the levels reported in primary tumors, and Y2R expression was high in tissues derived from local relapses, suggesting that this receptor is involved in cancer cell invasiveness." (PMID 37373115, 2023). "In Ewing’s sarcoma, DPPs could prevent cell death by cleaving (neuropeptide Y) NPY, and inhibition of DPP8/9 can activate poly (ADP-ribose) polymerase (PARP-1) and apoptosis-inducing factor (AIF)-mediated apoptosis pathway." (PMID 36172198, 2022). "In contrast, in Ewing's sarcoma, NPY induces tumor cell apoptosis via Y1 and Y5Rs." (PMID 20508839, 2010). "Moreover, NPY, via Y1R/Y5R, promoted the death of tumor cells in Ewing sarcoma, but under hypoxia, NPY acted as a tumor growth-promoting agent because these conditions favored Y2R expression and the formation of NPY3-36 that served as a Y2R/Y5R agonist and favored the migration of tumor cells." (PMID 37373115, 2023).